FGFR4 (fibroblast growth factor receptor 4)
Diseases named in the same sentence as FGFR4 in open-access papers (continued):
Sharing a sentence is not in itself a finding about the gene and the disease.
osteosarcoma (2 papers, 2023 to 2025). A usually aggressive malignant bone-forming mesenchymal neoplasm, predominantly affecting adolescents and young adults. "The main objective of this experiment was our desire to find a method that combines 2D-QSAR and 3D-QSAR to design more reliable compounds targeting osteosarcoma fibroblast growth factor receptor 4 (FGFR4)." (PMID 36895941, 2023). "Several compounds with optimal activity were used for docking experiments with osteosarcoma related targets (FGFR4)." (PMID 36895941, 2023). "Quinazoline derivatives exert an inhibitory effect on osteosarcoma growth by inhibiting the phosphorylation and signaling pathways of FGFR4." (PMID 36895941, 2023). "Activated FGFR4 interacts with fibroblast growth factor receptor substrate 2 (FRS2), recruits growth factor receptor binding protein (GRB2) and affects downstream proteins mediating osteosarcoma cell proliferation." (PMID 36895941, 2023).
Salmonella Infections (2 papers, 2013 to 2021). Infections with bacteria of the genus SALMONELLA. "In addition, Salmonella infection causes a substantial decrease in the expression of intestinal Fgf15, accompanied by a dramatic loss of hepatic FGFR4 and βKlotho." (PMID 24165751, 2013). "To determine if Salmonella infection disturbs the homeostasis of this pathway, we analyzed the levels of FGFR4 and βKlotho in infected and uninfected livers." (PMID 24165751, 2013).
serous ovarian carcinoma (2 papers, 2024 to 2025). "High expression levels of FGFR4 and FGF19, which is one of the ligands with the highest affinity and specificity to FGFR4, together can provide an even better prognostic marker for advanced stage high-grade serous ovarian carcinoma." (PMID 39858026, 2025). "Moreover, the FGF19/FGFR4 axis was correlated with poor prognosis in advanced high-grade serous ovarian cancer." (PMID 38273381, 2024).
small intestinal cancer (2 papers, 2012 to 2022). "Compared to normal tissues, FGFR4 expression was elevated in liver, colorectal, stomach, esophageal, and testicular cancers, but diminished in kidney, lung, lymphoid, and small intestine cancers." (PMID 22615798, 2012). "FGFR4 SVs/REs most commonly occurred in small intestinal cancer (SVs: 16/2434, 0.7%; REs: 0)." (PMID 36462464, 2022).
stomach cancer (2 papers, 2019 to 2022). "Here, we report the identification of an oncogenic mutation in FGFR4 in a human gastric tumour that leads to constitutive activation of its product, FGFR4." (PMID 31601997, 2019).
viral infections (2 papers, 2015 to 2024). "Among the top 10 downregulated genes, SREBF1, FGFR4, CRAT and PXMP4 showed a similar decrease following different viral infections." (PMID 39625479, 2024).
adrenocortical adenomas (1 paper, 2022). "As expectedly, nuclear p-S727 STAT3 positive cells were found in the adrenocortical adenoma components in Cases 1 and 3 (Case 3 > Case 1) in association with FGFR4 variant status, while no tyrosine phosphorylation of STAT3, a downstream signal of wild-type FGFR4, was found in any tumors." (PMID 35660748, 2022).
adrenocortical tumors (1 paper, 2014). "Additionally, the amplification of the IGFBP3, FGFR4 (data not shown), and NSD1 (data not shown) genes was also detected in this carcinoma, but IGF1R amplification was not demonstrated in the remaining cases with adrenocortical tumors." (PMID 25110710, 2014).
Airway obstruction (1 paper, 2020). Obstruction of conducting airways of the lung. "Using flexiVent to analyze lung function, Fgfr4−/− lungs showed a significant increase in static compliance and a marked decrease in the FEV0.05/FVC ratio, indicating airway obstruction." (PMID 32793609, 2020).
Alzheimer disease (1 paper, 2020). A progressive, neurodegenerative disease characterized by loss of function and death of nerve cells in several areas of the brain leading to loss of cognitive function such as memory and language. "Perhaps a more interesting ontological category is the 11 downregulated genes associated with MAPK signaling pathway, a number of which (Arrb2, Cacna1g, Fgfr4, Taok1, Cacna1h) have been implicated in Alzheimer's disease (AD)." (PMID 33282900, 2020).
Calcium nephrolithiasis (1 paper, 2019). The presence of calcium-containing calculi (stones) in the kidneys. "Consistent with previous studies, FGFR4 signaling is critical for the development of Calcium Nephrolithiasis." (PMID 31754202, 2019).
cerebral tumors (1 paper, 2025). "Furthermore, cerebral tumors may rely on FGFR4-driven angiogenesis to promote blood vessel formation." (PMID 40393028, 2025).
chronic myeloid leukemia (1 paper, 2017). "Importantly, targeting FGF19/FGFR4 axis by ponatinib, a third-generation inhibitor of chronic myeloid leukemia, overcomes HCC resistance of sorafenib by enhancing ROS-associated apoptosis in sorafenib-treated HCC." (PMID 28069043, 2017).
Chylothorax (1 paper, 2025). The presence of chyle in the thoracic cavity. "STLAM6 exhibited similar systemic involvement, including pleural effusions, chylothorax, and abdominal lymphadenopathy, with a 49% FGFR4 variant frequency, but no detectable TSC2 mutation." (PMID 40776927, 2025).
clear cell carcinoma (1 paper, 2023). "We analysed the expression of FGFR4 in 74 human clear cell carcinoma surgical specimens from patients with renal cancer using immunohistochemical staining." (PMID 36803783, 2023).
clear cell renal cell carcinoma (1 paper, 2023). "Several clear cell renal cell carcinoma (ccRCC) cases harbour fibroblast growth factor receptor 4 (FGFR4) gene copy number (CN) gains." (PMID 36803783, 2023).
COVID-19 (1 paper, 2023). A disease caused by infection with severe acute respiratory syndrome coronavirus 2. "It is, therefore, plausible that in view of the widely dysregulated inflammatory response that occurs in the setting of COVID-19, activation of "abnormal" FGFR4-dependent signaling in other cell types and tissues takes place." (PMID 37637614, 2023).
cystic lung disease (1 paper, 2025). "Patients STLAM4, STLAM5, and STLAM7 did not carry the FGFR4 variant but exhibited cystic lung disease in the absence of detectable systemic TSC2 mutations." (PMID 40776927, 2025).
gastric adenocarcinoma (1 paper, 2024). "Because the LIF/LIFR complex promotes an oncogenic development in several cancers, and the expression of LIF mRNA correlates with expression of FGFR4 in GC, then we saought to investigate whether the LIF regulates the expression of the FGFR4 in gastric adenocarcinoma cell lines." (PMID 37945798, 2024).
gliosarcoma (1 paper, 2022). A rare histological variant of glioblastoma (WHO grade IV) characterized by a biphasic tissue pattern with alternating areas displaying glial and mesenchymal differentiation (WHO). "Moreover, one GBM patient treated at our clinic presented with repeated recurrences accompanied by steadily increasing FGFR4 levels and a histological change towards a gliosarcoma." (PMID 35484633, 2022).
glycosylation disorders (1 paper, 2025). "Lastly, CD4 is connected to glycosylation disorders, reproductive processes, and FGFR4 signaling." (PMID 40787634, 2025).
hemangioblastoma (1 paper, 2025). "In conclusion, our study highlighted the frequent expression of FGFR2 and FGFR4 in hemangioblastoma and revealed a correlation between larger tumor size and increased FGFR4 expression, suggesting their roles in tumor development and growth." (PMID 40393028, 2025). "Our study revealed the expression of FGFR2 and FGFR4 in a significant number of hemangioblastomas." (PMID 40393028, 2025). "Furthermore, a positive correlation was identified between tumor size and FGFR4 expression, suggesting a possible role of FGFR4 in tumor progression in hemangioblastoma." (PMID 40393028, 2025).
idiopathic pulmonary fibrosis (1 paper, 2022). Idiopathic pulmonary fibrosis (IPF) is a nonneoplastic pulmonary disease that is characterized by the formation of scar tissue within the lungs in the absence of any known cause. "Additionally, lower FGFR4 expression at the mRNA and protein levels was reported in lung tissues obtained from patients with idiopathic pulmonary fibrosis (IPF) compared with control patients." (PMID 36142417, 2022).
invasive carcinoma of the (1 paper, 2021). "This organoid line was derived from a multifocal pT2 N1, grade 3 invasive carcinoma of the breast, which also scored positive for FGFR4 expression." (PMID 34344433, 2021).
irritable bowel syndrome (1 paper, 2021). Irritable bowel syndrome (IBS) is a chronic functional condition of the lower gastrointestinal (GI) tract characterized by abdominal pain or discomfort and disordered bowel habit (diarrhea, constipation, or fluctuation between the two). "This FGFR4 SNP in combination with another Klothoβ gene variant was previously shown to link bile acid homeostasis to colonic transit in irritable bowel syndrome (IBS) with diarrhea." (PMID 34071523, 2021).
kidney damage (1 paper, 2025). "Contrariwise, mice with a single amino acid substitution-induced constitutive gain-of-function mutation in Fgfr4 develop LVH without kidney damage or increased FGF23 levels." (PMID 39807363, 2025).
laryngeal squamous cell carcinoma (1 paper, 2025). A squamous cell carcinoma that arises from the larynx. "While the precise mechanism by which Fgfr2 deficiency affects Fgfr1 and Fgfr4 mRNA expression remains unclear, a positive correlation between FGFR1 and FGFR2 expression has been documented in human laryngeal squamous cell carcinoma tissues." (PMID 41151533, 2025).
lentivirus infection (1 paper, 2019). Virus diseases caused by the Lentivirus genus. "Corroborating the in vivo study, stable FGFR4 KO NCM460 cells were set up through lentivirus infection, WT and FGFR4 KO NCM460 cells were both exposed to PM for 30 passages." (PMID 31179224, 2019).
lipid metabolic disorder (1 paper, 2018). "The data from NASH-HCC mice suggested that aberrant FGF15/FGFR4 signaling and lipid metabolic disorder contributed to tumor-initiation for the carcinogenetic process." (PMID 29973237, 2018). "Up-regulated FGF15/FGFR4 signaling promoted the development of HCC by activation of EMT and Wnt/β-catenin signaling in the lipid metabolic disorder microenvironment." (PMID 29973237, 2018).
myocardial ischemia (1 paper, 2016). A disorder of cardiac function caused by insufficient blood flow to the muscle tissue of the heart. "A recent study confirmed that FGF23 can bind FGFR4 in cardiomyocytes to enhance hypertrophy, interestingly, our data in this study showing that FGFR4 is also expressed in cardiac fibroblasts and upregulated in response to myocardial ischemia." (PMID 27579618, 2016). "It is unclear why FGF23 did not exert profibrotic effect in sham mice, the upregulated FGFR4 in response to myocardial ischemia may be attributable." (PMID 27579618, 2016).
neutropenia (1 paper, 2025). A decrease in the number of neutrophils found in the blood. "Furthermore, UGT2B7_rs76688282 was correlated with both FN and prolonged severe neutropenia, while FGFR4_rs351855 was linked to the development of FN." (PMID 40227705, 2025).
oesophageal cancers (1 paper, 2023). "Several studies have reported FGFR4 as a potential therapeutic target in hepatic, ovarian, and oesophageal cancers." (PMID 36803783, 2023). "Furthermore, several studies have demonstrated that FGFR4 inhibition suppresses tumour growth in hepatocellular, ovarian, and oesophageal cancers." (PMID 36803783, 2023).
oropharyngeal squamous cell carcinomas (1 paper, 2012). "DNA from peripheral blood of 122 patients with oral and oropharyngeal squamous cell carcinomas was used to determine FGFR4 genotype by PCR-RFLP." (PMID 23226373, 2012).
oropharynx carcinomas (1 paper, 2012). A primary or metastatic malignant neoplasm that affects the oropharynx. "The present study evaluated the prognostic significance of FGFR4 in oral and oropharynx carcinomas, finding an association of FGFR4 expression and Gly388Arg genotype with tumor onset and prognosis." (PMID 23226373, 2012). "The present study evaluated the prognostic significance of FGFR4 expression and the Gly388Arg genotype in oral and oropharynx carcinomas in regard to tumor onset and prognosis." (PMID 23226373, 2012).
osteoporosis (1 paper, 2025). A condition of reduced bone mass, with decreased cortical thickness and a decrease in the number and size of the trabeculae of cancellous bone (but normal chemical composition), resulting in increased fracture incidence. "FGFR2 (rs199545667, rs4752570) were linked to HTN and osteoporosis, and to height and HTN; FGFR4 (rs351855), a missense variant, was linked to HTN and height." (PMID 41573461, 2025).
pediatric cancers (1 paper, 2025). "Using a broad search of all pediatric cancers, we observed the rates of alterations of the FGFR1, FGFR2, FGFR3, and FGFR4 genes in pediatric cancers to be 0.5%, 0.1%, 1.1%, and 0.8%, respectively." (PMID 40510032, 2025).
penile cancer (1 paper, 2022). A primary or metastatic malignant neoplasm that affects the penis. "We found FGFR4 mutations in all our penile cancer cell lines." (PMID 36564761, 2022).
penile squamous cell carcinoma (1 paper, 2022). "FGFR4 alterations were also described in penile squamous cell carcinoma cell lines." (PMID 36564761, 2022).
persistent atrial fibrillation (1 paper, 2021). "It was speculated that FGF-23/FGFR4 pathway may play an important role in promoting atrial fibrillation by atrial fibrosis." (PMID 33748139, 2021). "A total of 39 of 51 patients with rheumatic heart disease had persistent atrial fibrillation, the expressions of FGF-23 and FGFR4 were increased in patients with atrial fibrillation, which were positively correlated with atrial fibrosis." (PMID 33748139, 2021). "FGF-23 combined with FGFR4 produced ROS, activated downstream STAT3 and Smad3 proteins, and stimulated expression of matrix metalloprotein-2 (MMP-2) in myocardial tissue of patients with atrial fibrillation, leading to myocardial fibrosis." (PMID 33748139, 2021).
Pleural effusion (1 paper, 2025). The presence of an excessive amount of fluid in the pleural cavity. "STLAM2 also carried the FGFR4 variant at 49% allelic frequency and presented with cystic lung changes, pleural effusions, and renal angiomyolipomas (AML), also receiving sirolimus." (PMID 40776927, 2025).
polycystic ovary syndrome (1 paper, 2025). A disorder that manifests as multiple cysts on the ovaries. "This study investigated the roles of FGF19 in polycystic ovary syndrome (PCOS) and its associated molecular mechanisms, specifically focusing on the FGFR4-ERK-NRF2 pathway." (PMID 40950398, 2025).
prostate tumors (1 paper, 2017). "Dysregulation of FGFR4 activity has been observed in human epithelial carcinomas including head and neck, thyroid, breast, hepatocellular, and prostate tumors." (PMID 29221201, 2017).
RASopathies (1 paper, 2020). "In distinction to the known RASopathies, which are single gene disorders, the 6p25.1p24.3 microdeletion syndrome arises via transcriptional dysregulation of multiple RREB1 target genes including FGFR4, HRAS and MAP2K2 that result in sensitization of the MAPK pathway to activation." (PMID 32938917, 2020).
rectum adenocarcinoma (1 paper, 2020). An adenocarcinoma arising from the rectum. "FGFR4 was significantly upregulated in BRCA, COAD, HNSC, rectum adenocarcinoma (READ), and stomach adenocarcinoma (STAD) and was downregulated in KICH, LUAD, and LUSC." (PMID 32596330, 2020).
renal dysfunction (1 paper, 2021). "Fibroblast growth factor 23 (FGF23) is increased in both renal dysfunction and cardiac dysfunction, and FGF receptor 4 (FGFR4) has been identified as a receptor for FGF23." (PMID 33460402, 2021).
reproductive system cancer (1 paper, 2019). "Previously, we reported that the expression levels of FGFRs between carcinoma and para-carcinoma cells in patients with digestive or reproductive system cancers are significantly different, and FGFR2 and FGFR4 are closely related to the susceptibility of digestive and reproductive system cancers." (PMID 31523191, 2019).
Right ventricular hypertrophy (1 paper, 2020). In this case the right ventricle is more muscular than normal, causing a characteristic boot-shaped (coeur-en-sabot) appearance as seen on anterior- posterior chest x-rays. "This study demonstrates that global FGFR4 deficiency can cause airway pathology and right ventricular hypertrophy in the adult mouse, thereby indicating that FGFR4 signaling in the lung is essential and not only harmful as we have shown in preexisting airway diseases such as COPD." (PMID 32793609, 2020). "In addition to the inflammatory lung phenotype, 6-month-old Fgfr4−/− mice demonstrated an increase in right ventricular pressure as assessed by right heart catheterization and evidence of right ventricular hypertrophy as assessed by the Fulton index, when compared with their age-matched littermates." (PMID 32793609, 2020).
sensorineural hearing loss (1 paper, 2019). "In humans, HMX3 and HMX2 are located together, close to FGFR4, on chromosome 10; hemizygous microdeletions that remove all three genes are thought to be causative for syndromes characterised by inner ear morphological anomalies, vestibular dysfunction and sensorineural hearing loss." (PMID 31022185, 2019).
small cell lung carcinoma (1 paper, 2020). Small cell lung cancer (SCLC) is a highly aggressive malignant neoplasm, accounting for 10-15% of lung cancer cases, characterized byrapid growth, and early metastasis.
Stroke (1 paper, 2020). Sudden impairment of blood flow to a part of the brain due to occlusion or rupture of an artery to the brain. "The rs351855G/A (Gly388Arg) polymorphism and homozygous rs351855AA genotypic variations in FGFR4 have previously been found to increase susceptibility to stroke." (PMID 33447134, 2020). "This research also found a significant under-representation of JunD, NCX3 and FGFR4 annotated to GO biological processes, which may significantly impact stroke pathophysiology and subsequent clinical outcomes." (PMID 33447134, 2020).
thyroid dyshormonogenesis 1 (1 paper, 2024). "In the enrichment analysis, 13 signal transduction pathways, including FGFR4 mutant receptor activation and Defective SLC5A5 causing thyroid dyshormonogenesis 1, were involved in the effect of selenium on eGFR levels." (PMID 39329105, 2024).
tongue tumor (1 paper, 2021). "The therapeutic efficacy of FGF19/FGFR4 inhibition in melatonin-mediated tumor growth and metastasis was evaluated in orthotopic tongue tumor mice." (PMID 33691750, 2021).